TERT (telomerase reverse transcriptase)
Diseases named in the same sentence as TERT in open-access papers (continued):
Sharing a sentence is not in itself a finding about the gene and the disease.
tumor (continued). "Overexpression of these miRNAs in the tumor microenvironment might enhance immunogenicity and improve the outcome of ICI therapies, not only in advanced cases but also in cisplatin ineligible, in primary or recurrent NMIBC where high level of TERT and PD-L1 can be detected." (PMID 35223454, 2021). "It is possible that TERT upregulation might be an early event in ETT and that LPCAT1-TERT fusion might represent a later event capable of driving disease aggressiveness as has been observed for alternative TERT promoting events in tumor types where an LPCAT1-TERT fusion has been reported." (PMID 34033669, 2021). "However, in MCF-7 tumor cells no GABPA was detected on the TERT promoter." (PMID 33257697, 2020). "The current study suggested that TERT promoter mutations more likely tended to present in older patients with FTC, and were only associated with distant metastasis and advanced TNM stage, but not with gender, tumor size, multifocality, vascular invasion, extrathyroidal extension, and LNM." (PMID 31655978, 2020). "Finally, mice that completely suppressed tumor growth demonstrated no T cell response to TERT, either autoepitope TERT2 or CD4+ and CD8+ T cell epitopes represented by TERT1, TERT6, and TERT8, i.e., the rejection was not dependent on the adaptive immune response." (PMID 32570805, 2020). "Therefore, the methylation status of 8 selected TSGs and the TERT promoter should be a common feature of hepatocarcinogenesis, but may not necessarily reflect an aggressive tumor phenotype." (PMID 30274313, 2018). "In this review, we address seven different TMMs in tumour cells: mutations of the TERT promoter (TERTp), amplification of the genes TERT and TERC, polymorphic variants of the TERT gene and of its promoter, rearrangements of the TERT gene, epigenetic changes, ALT, and non-defined TMM (NDTMM)." (PMID 29751586, 2018). "Therefore, we first determined levels of TERT mRNA and/or telomerase activity in 6 MCC cell lines and 43 tumors [33 formalin-fixed, paraffin-embedded (FFPE) and 15 frozen samples; both FFPE and frozen tumor samples were available from 5 patients] obtained from 35 patients with MCC." (PMID 25301727, 2014). "The second interesting hypothesis is that the tumor cells are telomerase positive not because of TERT expression under a selective pressure, but because they are derived from the oncogenic transformation of a stem cell or a pluripotent early precursor cell which has retained its telomerase activity." (PMID 24152672, 2013). "Furthermore, both TERT and TINF2 have been suggested as potential therapeutic targets in human cancer and increasing our understanding of the role of these genes in Devil Facial Tumour Disease may open novel avenues for disease treatment." (PMID 22952882, 2012). "Despite the strong evidence that MYC is important, the requirements may differ when the selection conditions are changed, and we have preliminary evidence that MYC may not be required in ERα/BMI/TERT-transduced HMECs, at least for the initial stages of tumour formation." (PMID 17573968, 2007). "Differential expression of small-RNA from TERT altered and ATRX altered tumours with non-metastatic primary tumours revealed down-regulation (adj." (PMID 40097403, 2025). "p < 0.05, log fold-change > 1.5) in both TERT altered and ATRX altered tumours relative to non-metastatic primaries." (PMID 40097403, 2025). "Consistent with previous findings, the present study revealed higher expression levels of TERT and TERC, and increased TA and TL in CRC tumor tissue compared to adjacent non-tumor tissue." (PMID 39222177, 2025). "Contrasting the TERT and ATRX-altered tumours to non-metastatic tumours we found 1,152 and 1,448 differentially expressed genes, respectively." (PMID 38978571, 2024).
tumor (continued). "Contrary to the idea that antigen may drive the formation of TLS, our data support the view that TERT overexpression in HNSCC tumors may not be solely responsible for the formation of TLS since a Bhigh/TERThigh signature drives comparable TLS scores in other tumor types." (PMID 36909826, 2023). "Taking this into account, it is not surprising that there is a concomitant expression of TERT and ACE2 mRNA in tumours with lymphocytic infiltration." (PMID 37568724, 2023). "Because GABPB1 is a subunit of GABP, which binds to the mutant TERT promoter without interfering with the normal TERT promoter, GABPB1 is viewed as a tumor-specific therapeutic approach with potentially limited toxicity." (PMID 36997627, 2023). "The diagnosis of oligosarcoma can be established by the combination of an IDH-mutant tumor with at least partial (leiomyo)sarcomatous differentiation which harbors a 1p/19q LOH which may be copy number neutral and typically (but not always) a TERT promoter mutation." (PMID 34967922, 2022). "Firstly, other important tumor-related biomarkers like O6-methylguanine-DNA methyltransferase (MGMT) and telomerase reverse transcriptase (TERT) status that were related to prognosis were not included in the study due to insufficient pathological data." (PMID 35488347, 2022). "Moreover, the present study highlighted that the tumor-suppressive functions of GABPB1 may be independent of the TERT promoter since we found a similar enhanced invasive ability after inhibition of GABPB1 in TC cells regardless of their TERT promoter mutation status." (PMID 35326537, 2022). "For the ALT-dependent neoplasms occurring in SOT patients, circulating TERT mRNA detection would not be informative, therefore other blood-based biomarkers of tumor development need to be investigated." (PMID 34746013, 2021). "It is known that in non-MYCN-amplified NB displaying 5p15 gains, TERT expression increases, functioning in lieu of MYCN amplification to promote tumor progression." (PMID 34830942, 2021). "Genetic analysis of primary tumour revealed KRAS Q61K, wild-type IDH1/2, H3F3A, HIST1H3B and TERT promoter, and no MGMT promoter hypermethylation." (PMID 34525976, 2021). "Tissue microarray data showed that the expression of NCOA3 and TERT were positively correlated in HCC patients (n = 53), and were higher in tumor tissues than in adjacent nontumor tissues." (PMID 33239622, 2020). "Compared to Survivin/BIRC5 and TERT, the expression of CXCR4 resulted not adequately selective for tumour samples versus healthy tissues." (PMID 32152425, 2020). "Even the introduction of TERT and SV40 or HPV-16 E6/E7 was sufficient to immortalize ovarian surface epithelial cells and dermal papilla cells but not enough for tumor formation." (PMID 30627420, 2019). "Of the seven remaining ALT-negative tumors that lacked TERT rearrangement, one tumor harbored amplification of MYC, a known transcriptional activator of TERT31, and this tumor displayed elevated TERT expression (arrow)." (PMID 29802247, 2018). "We also assessed the potential tumorigenicity of TERT-SHED, and found that TERT-SHED at late passage showed low tumorigenicity, as indicated by normal karyotype, no soft agar colony formation, and no tumor formation in nude mice." (PMID 27044500, 2016). "These genes regulate tumor onset and progression, further indicating a possible link between RRM and its interactors to TERT non-telomeric functions." (PMID 26617625, 2015). "A previous study reported detectable telomerase activity in tumor biopsies derived from 4 MCC patients, whereas TERT mRNA expression in MCC has not been investigated so far." (PMID 25301727, 2014). "Likewise, the coexistence of TERT amplification and TPM was seen in five of the 11 patients who developed recurrences and finally DOD, but in none of the patients with tumor recurrence who were AWD or showed no signs of tumor disease." (PMID 40272676, 2025).
tumor (continued). "Indeed, enrichment of TNC+ EVs significantlyimproved the detected frequencies of TERT*C228T,reinforcing that the majority of TNC+ EVs in plasma fromglioblastoma patients are specifically released from tumor cells,unlike TNC– EVs." (PMID 40056466, 2025). "However, given the possible presence of heterogeneous MNA where neoplastic cells with and without MNA co-exist within the tumor, the limitation of the used methods does not allow us to deduce if MNA and TERT are present in the same cell population." (PMID 38136279, 2023). "Noticeably, overexpressed NYESO1 (CTAGB1), MUC1, MAGEA3, MAGEA4, or CEA (CEACAM5) antigens did not correlate with TERT improved PFS of patients with high B cell infiltrate, suggesting a selective role of TERT over other common tumor antigens in driving local antitumor immunity." (PMID 36909826, 2023). "While the mean age, gender distribution, preoperative KPS score, mean tumor volume, the incidence of ventricle infringement, MGMT promoter status, EFGR amplification, tumor location, and TERT promoter status was not different between discordant and accordant patients." (PMID 35185770, 2022). "The recent next-generation sequencing data suggest that the integration of the viral genome in the non-tumor tissue is dispersed throughout the genome with no hotspot while tumor tissue showed enrichment of particular genomic sites such as MLL4, TERT, and CTNNB1." (PMID 34526974, 2021). "First, the different TMMs, i.e., TERT expression and the ALT pathway have different metabolic signatures, suggesting that the metabolic alterations are not simply the result of telomere maintenance-mediated tumor proliferation." (PMID 33397920, 2021). "Interestingly, investigation of in silico data rather showed a trend towards lower TERT mRNA expression in BRAF-mutant GBM, but not other BRAF-mutant tumor types." (PMID 31391125, 2019). "Thus, the BRAF V600E mutation is associated with older age and conventional PTC but not more established prognosticators such as tumor size, multifocality, or TNM stage in TERT promoter-negative cases." (PMID 27064992, 2016). "Therefore, it is reasonable that lentiviral vector-mediated TERT expression had low tumorigenicity in SHED at late passage, as indicated by no abnormal karyotype, no colony formation in soft agar, and no tumor formation in nude mice." (PMID 27044500, 2016). "Moreover, TERT-SHED at late passage showed normal karyotype, no soft agar colony formation, and no tumor formation in nude mice." (PMID 27044500, 2016). "Similarly, telomerase reverse transcriptase (TERT) can activate endogenous retroviruses (ERV) independent of its telomerase activity to form double-stranded RNA, which is sensed by the MDA5-MAVS pathway and triggers IFN signals in tumor cells." (PMID 36119095, 2022). "Among them, the enrichment of HBV-DNA integration in TERT, CCNE1, and CCNA2 genes in tumoral samples has also been confirmed by analyzing the publicly available database VISDB, collecting 20558 HBV-DNA integration sites in tumor/peritumor/non-tumor liver samples from 45 publications." (PMID 36118192, 2022).
cancer (1,347 papers, 2003 to 2026). A tumor composed of atypical neoplastic, often pleomorphic cells that invade other tissues. "The genetic screens in GBM have identified mutations commonly found across various cancers, such as TERT dependency." (PMID 41139700, 2026). "Oncogenic variants in TERT promoter, especially -124C > T, have been well documented in various types of cancers, including HNSCC." (PMID 41489678, 2026). "TERT promoter mutations represent one of the most frequent somatic genetic alterations in human cancers." (PMID 41293148, 2025). "A pan-cancer analysis demonstrates that the expression variability of TERT is correlated with multiple cancer types and is associated with DNA methylation and immune cell infiltration." (PMID 40070565, 2025). "Of special interest were low-grade non-invasive papillary carcinomas, in which TERT promoter mutations were more common (77%) than in carcinoma in situ and high-grade non-invasive cancer (65%), a statistically significant result (p = 0.017)." (PMID 40282460, 2025). "It means that TERT plays a pivotal role in cancer progression and is intricately linked to glucose metabolism." (PMID 39940762, 2025). "C228T and C250T mutations in the TERT promoter region (TERT-p) occur in numerous cancers and result in the production of the TERT protein, leading to cell immortalisation, a hallmark of cancer cells." (PMID 40361475, 2025). "We found that patients with a TERT promoter mutation tended to have longer survival, slower disease progression, and lower levels of a common blood marker used to monitor cancer." (PMID 40862791, 2025). "Cancers with TERT promoter mutations (TPM) display elevated RAS pathway signaling and mesenchymal traits, and associate with lower patient survival rates." (PMID 40560846, 2025). "This interaction upregulates TERT-associated tRNAs in cancer cells, amplifying its pro-tumorigenic activities." (PMID 39871386, 2025). "In conclusion, our multi-faceted study uncovers the complex regulation of TERT functions and multi-cancer cancer risk through a combination of TERT germline variants – an SNP rs10069690 within intron 4 and a VNTR within intron 6 (VNTR6-1)." (PMID 39956830, 2025). "Genetic regions including 5p15.33 (TERT) and 6p21-22 (HLA) also showed wide evidence of pairwise pleiotropy in multiple cancer combinations for individual variants." (PMID 40019942, 2025). "TERT contribution to the onset and development of cancer has been usually associated with its main function of telomeric DNA elongation, conferring unlimited proliferative ability to normal cells." (PMID 41144538, 2025). "Whole-genome and RNA sequencing of a broad panel of cancer cell lines revealed 60 lineages (18.23%) harboring TERT promoter mutations, all of which exhibited monoallelic TERT mRNA expression driven by the mutated TERTp." (PMID 41487579, 2025). "The high mutation frequency of the TERT promoter in low-grade noninvasive cancer supports its application for early detection and the addition of other oncogenic mutations enhances its sensitivity for high-grade and muscle-invasive BCa." (PMID 40282460, 2025). "Mutations in the TERT gene can activate telomerase and promote uncontrolled cell proliferation, which can contribute to the development and progression of cancer." (PMID 39744583, 2025). "The proliferative immortality of cancer cells is attained through the activation or upregulation of the normally silent human telomerase reverse transcriptase (TERT) gene (hTERT), which encodes telomerase." (PMID 40151802, 2025). "Nonetheless, TA, persists in these cancers, suggesting the existence of additional, yet-undiscovered mechanisms underlying TERT upregulation." (PMID 39871386, 2025).
cancer (continued). "Cancers with TERT promoter mutations and high expression of TERT are associated with poor outcome, making them and the telomer shortening, an interesting drug target." (PMID 39762846, 2025). "Using genome-wide pleiotropy and colocalization analysis, we identified 60 colocalized susceptibility loci shared by CAD and site-specific cancer, of which 43 are novel, including loci at TERT, MYO9B, and SREBF1." (PMID 40874306, 2025). "It has been observed that telomere maintenance genes (TMGs) influence cancer occurrence by regulating mutations in the telomerase reverse transcriptase (TERT) promoter, suggesting their potential as cancer biomarkers." (PMID 40613523, 2025). "Concerning the relationship of uPAR and TREM1 with the telomere system, one study showed that uPA (the ligand for uPAR) is positively associated with the TERT component of TE and that hTERT enhances uPA expression in cancer cells." (PMID 40149509, 2025). "Several multi-cancer GWAS loci within the region encoding telomerase reverse transcriptase (TERT) have been identified." (PMID 39956830, 2025). "Recent research has indicated that the transcriptional activity of TERT is closely associated with the methylation status of its promoter region, particularly in cancer cells." (PMID 40362481, 2025). "TERT promoter mutations have been reported in at least 50 cancer types and are associated with aggressive disease and poor clinical outcomes." (PMID 40711866, 2025). "This suggests that the subcellular distribution of telomerase and TERT is intricately linked to the survival of cancer cells." (PMID 39871386, 2025). "The role of TERT mutations in cancer has been a subject of controversy, as described in previous studies." (PMID 40141436, 2025). "These TERT promoter mutations are prevalent in many cancers but are rare in hematological malignancies." (PMID 40227701, 2025). "Mutations in the TERT promoter can reactivate the expression of telomerase, allowing for continued cell replication in cancers." (PMID 40507266, 2025). "Mutations in the TERT (telomerase reverse transcriptase) promoter are associated with increased telomerase activity, allowing cancer cells to maintain their telomeres and avoid senescence or apoptosis." (PMID 40344620, 2025). "These TERT promoter mutations (TPM) are among the most common cancer driver mutations so far discovered." (PMID 40560846, 2025). "Background/Objectives: Telomerase reverse transcriptase (TERT) is the catalytic subunit of the telomerase enzyme responsible for telomere length maintenance and is an important cancer hallmark." (PMID 39858033, 2025). "Co-occurrence with the BRAF V600E mutation amplifies TERT expression by activating ETS transcription factors, which bind to newly created ETS sites in the mutated TERT promoter, driving cancer cell immortality." (PMID 40332222, 2025). "Five FNA samples (83.33%, 5/6) with TERT mutations were identified as malignant tumors, while one was benign." (PMID 40586006, 2025). "For example, the promoter region of the TERT gene that encodes the catalytic subunit of telomerase is essential for telomerase expression in these cancers." (PMID 40560846, 2025). "In normal tissues with low replicative potential, including the bladder and brain, tumorigenesis often depends on driver mutations, such as TERT-upregulating promoter mutations that reactivate telomerase and immortalize cancer cells." (PMID 39956830, 2025). "Cancer cells activate telomerase to gain immortality by acquiring TERT promoter mutations and rearrangements, or transcriptional dysregulation." (PMID 41321994, 2025). "It is known that TERT activity is associated with telomerase function and is often elevated in cancer cells, allowing them to divide indefinitely." (PMID 40867242, 2025). "TERT promoter mutations lead to elevated telomerase expression, enabling various cancers to overcome the end-replication problem and evade senescence." (PMID 40995307, 2025).